TFAM (transcription factor A, mitochondrial)
Diseases named in the same sentence as TFAM in open-access papers (continued):
Sharing a sentence is not in itself a finding about the gene and the disease.
prion disease (1 paper, 2024). A transmissible disease that is caused by a protein that is able to induce abnormal folding of normal cellular proteins, leading to characteristic spongiform brain changes, which are associated with neuronal loss without an inflammatory response. "We demonstrated that the SIRT1-PGC-1α-TFAM signaling pathway promotes mitochondrial biogenesis in the prion disease cell model." (PMID 39273653, 2024). "In summary, impaired mitochondrial biogenesis regulated by the SIRT1-PGC-1α-TFAM pathway potentially contributes to mitochondrial damage and plays a critical role in the pathogenesis of prion diseases." (PMID 39273653, 2024). "Additionally, resveratrol emerges as a promising candidate for prion disease treatment, with its pharmacological effects primarily mediated via the SIRT1-PGC-1α-TFAM pathway." (PMID 39273653, 2024). "Our studies ultimately demonstrate that SIRT1 plays an important role in the regulation of mitochondrial biogenesis through the PGC-1α-TFAM pathway, and SIRT1 may represent a potential target for therapeutic intervention in prion diseases." (PMID 39273653, 2024).
progressive external ophthalmoplegia (1 paper, 2020). A mitochondrial myopathy characterized by slowly progressive paralysis of the levator palpebrae, orbicularis oculi, and extraocular muscles. "Several point mutations in the human RNASEH1 gene are associated with progressive external ophthalmoplegia, a syndromic disorder associated with mutations in various mtDNA maintenance proteins, such as the mitochondrial DNA polymerase gamma (Polγ) or mitochondrial transcription factor A (TFAM)." (PMID 32589740, 2020).
psoriasis (1 paper, 2022). An autoimmune condition characterized by red, well-delineated plaques with silvery scales that are usually on the extensor surfaces and scalp. "We found that the level of MDA was increased in diabetic mice with psoriasis, whereas TFAM, OXPHOS‐related proteins and the expression of mitochondrial‐related genes were significantly decreased." (PMID 35174638, 2022). "Using TFAM as a mtDNA biomarker, we also found that the expression of TFAM, mitochondrial OXPHOS proteins and ND6 was significantly reduced, suggesting that psoriasis with diabetes induces mitochondrial oxidative damage." (PMID 35174638, 2022).
renal tumor (1 paper, 2010). "Based on our findings, it is likely that a FLCN-PGC-1α-TFAM signaling axis exists and that lack of FLCN expression may be an important feature in sporadic tumors of other organs as it is in BHDS-derived renal tumors." (PMID 21162720, 2010).
serous carcinomas (1 paper, 2014). "By contrast, high-grade serous carcinomas were characterised by a converse state of PGC1α/TFAM, ERα positivity and a high Ki-67 index." (PMID 25243473, 2014).
Shock (1 paper, 2012). The state in which profound and widespread reduction of effective tissue perfusion leads first to reversible, and then if prolonged, to irreversible cellular injury. "Thus, TFAM can act as a DAMP and may contribute to the initiation of inflammatory responses after hemorrhagic shock." (PMID 22469910, 2012).
skin tumours (1 paper, 2021). "The mitochondrial biogenesis functions of the D-loop are regulated by the transcription factor TFAM (Transcription Factor A, Mitochondrial), which is transcribed from its nuclear gene, and also hypomethylated and expressed in PBMC in arsenic exposed populations and in arsenic-induced skin tumours." (PMID 34681626, 2021).
small cell lung carcinoma (1 paper, 2024). Small cell lung cancer (SCLC) is a highly aggressive malignant neoplasm, accounting for 10-15% of lung cancer cases, characterized byrapid growth, and early metastasis. "It has been shown that p21 is a possible target of TFAM, as disruption of TFAM in mouse skin fibroblasts and non-small cell lung cancer cells has led to elevated expression of p21 in previous studies." (PMID 39580766, 2024).
status epilepticus (1 paper, 2023). Status epilepticus is defined as a continuous seizure lasting more than 30 min, or two or more seizures without full recovery of consciousness between any of them. "Furthermore, resveratrol promoted mitochondrial biogenesis in a rat model of status epilepticus, by increasing protein expression of PGC-1α, NRF1, TFAM, as well as the mtDNA, and attenuation of neuronal cell damage in the hippocampus following status epilepticus." (PMID 36237161, 2023).
Stroke (1 paper, 2021). Sudden impairment of blood flow to a part of the brain due to occlusion or rupture of an artery to the brain. "In our stroke model, we observed a pronounced short-term PGC-1α activation, evidenced by a significant upregulation of PGC-1α-dependent proteins: NRF1, TFAM, catalytic subunits of the substrate-binding sites of the respiratory chain (NDUFV2 and SDHA), VEGF, and SYP." (PMID 33806692, 2021).
systemic lupus erythematosus (1 paper, 2020). An autoimmune multi-organ disease typically associated with vasculopathy and autoantibody production. "In systemic lupus erythematosus, mtDNA binding to the histone-like protein mitochondrial transcription factor A (TFAM) has shown to assist in rerouting oxidized mtDNA of neutrophils to lysosomes for degradation." (PMID 33304353, 2020).
systemic sclerosis (1 paper, 2026). A chronic disorder, possibly autoimmune, marked by excessive production of collagen which results in hardening and thickening of body tissues. "Furthermore, we see beneficial effects in cellular disease models in which boosting TFAM activity has been advanced as a disease-modifying strategy including improved energetics in MELAS cybrid cells and a decrease of fibrotic markers in systemic sclerosis fibroblasts." (PMID 41649246, 2026).
Tinnitus (1 paper, 2025). Tinnitus is an auditory perception that can be described as the experience of sound, in the ear or in the head, in the absence of external acoustic stimulation. "Another study demonstrated that a dose of 100 mg/kg of naringin significantly increased PGC1-α and TFAM expression in the hippocampus of male Wistar rats suffering from chronic tinnitus." (PMID 40842941, 2025).
tongue cancer (1 paper, 2021). A malignant neoplasm affecting the tongue. "In agreement with in vitro and in vivo findings, it was also found that TFAM and mtDNA encoded ETC genes were downregulated in Nqo treated mouse tongue cancer and clinic HNC tissues compared with their normal counterparts." (PMID 34663785, 2021).
vascular parkinsonism (1 paper, 2024). A Parkinsonism that is characterized by postural instability, a broad-based gait with the absence of tremors of vascular origin. "The genetic markers of vascular parkinsonism suchas TFAM, CASP3, ALBU, and VEGFA have a stronger regulatoryinfluence on acylcarnitine metabolism enzymes, whereasFBX7, NOTC3, and FA12 predominantly affect amino acidmetabolism enzymes." (PMID 39944797, 2024).
VHL syndrome (1 paper, 2022). "Here we show an oxygen-sensitive regulation of TFAM, an activator of mitochondrial transcription and replication, whose alteration is linked to tumours arising in the von Hippel–Lindau syndrome." (PMID 35760869, 2022). "Non-cancerous VHLR200W Chuvash polycythaemia mutation was normal with regard to TFAM regulation in contrast to all other VHL syndromic cancer mutations, which suggests that impaired mitochondrial biogenesis is an important feature of the VHL syndrome." (PMID 35760869, 2022).
tumor (95 papers, 2004 to 2026). "But, TFAM showed the higher expression in tumor tissues compared to normal tissues and was linked to poor prognosis." (PMID 41362737, 2026). "Recent studies implicate mtDNA depletion via TFAM mutation in fostering tumor progression as well as cisplatin resistance in microsatellite instability (MSI) CRC, with implications yet to be fully explored in microsatellite stable CRC." (PMID 41403952, 2025). "These divergent outcomes highlight that the impact of TFAM loss is context-dependent, shaped by the basal metabolic wiring of each tumor." (PMID 41226485, 2025). "Hypoxia in the tumor microenvironment not only drives tumor progression but is also linked to the suppression of TFAM expression." (PMID 41398603, 2025). "Our study demonstrates that overexpression of TFAM elevates mitochondrial ROS (mtROS) production and triggers tumor cell apoptosis, a process linked to mitochondrial hyperpolarization which a finding experimentally validated in our work." (PMID 41274938, 2025). "Clinicopathological analysis of 48 EOC patients showed that TFAM expression was significantly associated with tumor clinical stage (P = 0.004) and lymphatic metastasis (P = 0.043)." (PMID 39927160, 2025). "Our clinicopathological analysis results showed that TFAM expression was significantly associated with tumor clinical stage and lymphatic metastasis." (PMID 39927160, 2025). "TFAM overexpression in normal tissue can inhibit tumor development; however, TFAM expression is upregulated in colitis-associated cancer (CAC) tissues and contributes to cell growth." (PMID 38589371, 2024). "Conversely, mutations in TFAM or a decline in its activity can reduce mtDNA content, affect mitochondrial function, and thus promote tumor development." (PMID 39763669, 2024). "Together, these data suggest that PSAT1 is critical for the nuclear translocation of PGC-1α and thus promotes the transcription of TFAM in tumor cells expressing the p5372P variant." (PMID 36788227, 2023). "Studies have shown that downregulation of TFAM in fibroblasts results in the loss of the Caveolin 1 protein expression, a potent stromal biomarker for tumor progression." (PMID 38124183, 2023). "In Treg cells, the loss of mitochondrial transcription factor A (TFAM) is important for mitochondrial respiratory chain activity, impairs the accumulation and cell lineage stability of the tumour-infiltrating Treg cells, and thus, inhibits tumour growth." (PMID 36569832, 2022). "Mei indicated that reduced mtDNA copy numbers caused by TFAM knockdown sensitized the tumor cell lines HEp-2, HNE2, and A549 to chemotherapeutics." (PMID 30862036, 2019). "Human mitochondrial transcription factor A (TFAM) has been implicated in promoting tumor growth and invasion." (PMID 29259235, 2017). "In that way TFAM deficiency promotes the tumor-suppressive functions of the p21 protein." (PMID 39580766, 2024). "On the other hand, some studies suggest that downregulation of TFAM expression may be associated with tumor development." (PMID 38589371, 2024). "In agreement with database analysis, TFAM mRNA expression of all mtDNA encoded ETC genes were significantly downregulated in tumours compared with corresponding normal tissues, suggesting that decreased TFAM levels might be important for HNC development." (PMID 34663785, 2021). "Since post-translational modifications of TFAM significantly affect its stability or function, and its modifications may also be tightly associated with tumor progression." (PMID 32039210, 2020).
tumor (continued). "Our study results, together with previous findings, indicate that enhanced mitochondrial activity due to excessive TFAM may be associated with mitochondrial biogenesis-dependent tumor metastasis and poor patient survival." (PMID 29259235, 2017). "To further test whether TFAM expression is elevated in the tumor tissues and to determine its association with clinical and pathologic parameters of NSCLC patients, we performed IHC in TMA containing 150 archived paraffin-embedded NSCLC specimens." (PMID 26820294, 2016). "Intestinal-specific knockout of TFAM has been shown to prevent tumor formation in Apc-mutant mouse models of colon cancer." (PMID 41362737, 2026). "Our analysis reveals that TFAM functions as a critical node connecting mitochondrial integrity to tumor progression, balancing tumor-promoting and tumor-suppressive roles depending on the context." (PMID 41774266, 2026). "Both the SIRT6 overexpression group and the TFAM knockdown group showed significantly smaller tumor volumes compared to the control group." (PMID 41362737, 2026). "Several studies have shown that TFAM is abnormally expressed in various tumor tissues, and it is related to lymph node metastasis and tumor malignancy degree." (PMID 39927160, 2025). "By integrating phenotypic assays with transcriptomic profiling, distinct downstream effectors were revealed—including TRAF2 and LOXL2—that connect TFAM dysregulation to cell cycle control, metabolic reprogramming, and tumor invasiveness." (PMID 41226485, 2025). "Inhibition of TFAM led to a decrease in the expression of some of the mitochondrial complex subunits, which reversed the pro‐carcinogenic phenotype of the tumor." (PMID 40583735, 2025). "Together, these findings underscore that the biological consequences of TFAM dysregulation are highly context-dependent, shaped by the tumor’s intrinsic metabolic wiring and antioxidant defense capacity." (PMID 41226485, 2025). "Consistent with previous findings of our group, TFAM expression progressively decreased with increasing tumor grade, from AG2 to GBM." (PMID 41226485, 2025). "Required for TFAM-mediated mitochondrial respiration in T-cells to regulate inflammation and anti-tumor immunity." (PMID 38779771, 2024). "We selected male nude mice (BALB/C-nu/nu) as experimental subjects and constructed a mouse xenograft tumor model by subcutaneously injecting HepG2 cells or TFAM-overexpressed HepG2 cells." (PMID 39770569, 2024). "In terms of mechanism, CKIP‐1 silencing induced TFAM downregulation disrupted mitochondrial homeostasis to activate the tumour‐suppressing cGAS‐STING axis in OSCC cells." (PMID 39169452, 2024). "Overall, the role of TFAM in tumor development and progression is a complex area that requires further investigation." (PMID 38589371, 2024). "Since tumor cells tend to proliferate abruptly it is evident that TFAM is regarded as an oncogene and is highly expressed in malignant cells." (PMID 39188055, 2024). "Mitochondrial transcription factor A (TFAM) is required for mitochondrial homeostasis and is involved in the metabolic changes that occur in tumours." (PMID 39169452, 2024). "Deletion of the TFAM gene leads to mitochondrial dysfunction and reduces tumor incidence in a Kras-driven lung cancer mouse model." (PMID 38589371, 2024). "Consistent with this, TFAM expression was also significantly reduced in the nude mice tumour samples in sh‐CKIP‐1 group." (PMID 39169452, 2024). "The results of the Western blot revealed that the combination significantly reduced mitophagy-related proteins in tumor tissues, and overexpression of TFAM hindered this reduction." (PMID 39770569, 2024). "Knockdown of TFAM expression in non-small cell lung cancer inhibits tumor cell proliferation by activating the ROS-mediated JNK/p38MAPK signaling pathway and reducing cellular bioenergetic production." (PMID 38589371, 2024).
tumor (continued). "The inactivation of the mitochondrial transcription factor TFAM that depletes mitochondria from tumor cells impairs the K-ras lung tumor." (PMID 38612726, 2024). "The expression levels of mitochondria tumor-suppressor and DNA-repair proteins (PGC-1α, TFAM, OGG1, MTUS1, and SIRT3) were examined in tumor samples from patients with OSCC to determine the association of these proteins with patient outcomes." (PMID 37627097, 2023). "TFAM strongly regulates drug resistance (cisplatin) and tumor progression, by suppressing TFAM 3’UTR activity." (PMID 37067729, 2023). "Mitochondrial transcription factor A (TFAM) plays an important role in mitochondrial quality control, and imbalances in TFAM and/or mtDNA homeostasis are frequently observed in tumor cells." (PMID 37965570, 2023). "In contrast, chloroquine treatment significantly decreased the promotional effect of H-151 on xenograft tumor growth and cell proliferation in Drp1 overexpression or TFAM depletion." (PMID 35209954, 2022). "The tumor tissues of both stages of CRC showed a differential pattern in the levels of TFAM and PGC1α." (PMID 35205159, 2022). "TFAM is hydroxylated by EGLN3 and subsequently bound by the von Hippel–Lindau tumour-suppressor protein, which stabilizes TFAM by preventing mitochondrial proteolysis." (PMID 35760869, 2022). "Inhibiting the expression of TFAM can promote the sensitivity of tumor cell mitochondria to oxidative stress." (PMID 35326602, 2022). "For instance, TFAM is found to be aberrantly expressed in CRC cells and a high TFAM expression can serve as a useful marker for tumor progression in CRC patients." (PMID 34235078, 2021). "The expression of TFAM and its downstream targets was further examined in paired adjacent normal (N) and tumour (T) clinical tissues from HNC patients (N = 18)." (PMID 34663785, 2021). "In the present study, we discovered that lower TFAM and mtDNA expression led to decreased mitochondrial activity, which elicited oncogenic pathways to promote tumour proliferation, mobility and therapeutic sensitivity." (PMID 34663785, 2021). "The expression of PGC-1α and TFAM has been shown to vary between tumors and even between tumor subtypes, and evolving evidence indicates a role in chemoresistance, metastasis, survival etc.." (PMID 34964922, 2021). "Collectively, these studies indicate that high TFAM expression can be a potential marker for tumor progression in CRC patients." (PMID 34235078, 2021). "Collectively, TFAM expression negatively correlated with cell malignancy in HNCs, confirming that TFAM acts as a tumour-suppressing factor in HNCs." (PMID 34663785, 2021). "Studies have shown that TFAM plays a role as a tumor-promoting gene and is involved in the tumorigenesis, development, invasion and metastasis of tumors." (PMID 34823421, 2021). "In the current study, we identified that knockdown of TFAM repressed the synthesis of autophagy bio-marker LC3-II in tumor cells and decreased the expression of phosphatidyl-serine decarboxylase (PISD)." (PMID 32093281, 2020). "Based on these results, we concluded that PISD was key for autophagy flux in tumor cells, and its downregulation in TFAM knockdown tumor cells resulted in the inhibition of autophagy." (PMID 32093281, 2020). "In summary, our study discovered a new mechanism regarding disturbed autophagy in tumor cells with mitochondrial dysfunction due to the depletion of TFAM." (PMID 32093281, 2020). "In this research, we demonstrated the contribution of cyclooxygenase-2 (COX-2) to enhancing TFAM expression in irradiated tumor cells." (PMID 30862036, 2019). "Previous studies confirmed that reduced TFAM expression sensitized tumours cells to chemical therapy reagents and ionizing irradiation (IR)." (PMID 31062473, 2019). "In conclusion, our current work revealed a mechanism about the impact of mitochondrial function regulator TFAM on the sensitivity of tumour cells to ionizing radiation." (PMID 31062473, 2019).